LIF (LIF interleukin 6 family cytokine)
Diseases named in the same sentence as LIF in open-access papers (continued):
Sharing a sentence is not in itself a finding about the gene and the disease.
demyelinating disease (3 papers, 2010 to 2023). A broad group of disorders that affect the myelin sheaths that cover the neurons. "Studies in LIF knock-out mice and exogenous LIF administration have highlighted its protective action in many models of demyelination, suggesting the possible therapeutic use of LIF and LIF inducers in demyelinating diseases, including MS." (PMID 30261841, 2018). "Leukemia inhibitory factor (LIF) not only acts as a neurotrophic factor in CNS but also inhibits the production of oxygen radicals and TNF-α, and stimulates myelin uptake by macrophages, suggesting that LIF may be useful for treating CNS trauma or other demyelinating diseases." (PMID 20186338, 2010).
female infertility (3 papers, 2018 to 2022). Diminished or absent ability of a female to achieve conception. "Deregulated LIF expression is linked to several cases of female infertility that are associated with defective endometrial receptivity." (PMID 30109142, 2018). "Uterine conditional depletion of Foxa2 causes loss of leukemia inhibitory factor (LIF) secretion and female infertility." (PMID 35861728, 2022).
head and neck cancer (3 papers, 2016 to 2018). A primary or metastatic malignant neoplasm affecting the head and neck. "LIF is also recognized to play a critical role in the progression of several types of solid malignancies, including head and neck cancer." (PMID 29444110, 2018). "LIF is reportedly overexpressed in several kinds of human malignancies, including head and neck cancer; however, its expression in the cancer microenvironment is largely unknown." (PMID 29444110, 2018).
heart failure (3 papers, 2016 to 2025). Inability of the heart to pump blood at an adequate rate to meet tissue metabolic requirements. "Guizhi Decoction, Guizhi Decoction, comprising ingredients like Guizhi and ginger, improves myocardial fibrosis by modulating NGF and LIF levels, slowing heart failure progression." (PMID 40606601, 2025). "Similarly to our results, increased expression levels of ACE2, NRG1, DUSP4 and LIF have also been found in human heart failure." (PMID 26537877, 2016). "Our results suggest that the administration of LIF regenerates a substantial number of cardiomyocytes (approximately 1.96 ± 3.33 × 104 cardiomyocytes per heart) and may represent a potent therapeutic strategy for heart failure." (PMID 27227407, 2016).
liver steatosis (3 papers, 2022 to 2024). "However, this circulating LIF overexpression in HFD mice is associated to the alleviation of hepatic steatosis, notably via the inhibition of SREBP1-c expression through the activation of STAT3 pathway reducing hepatic triglycerides accumulation." (PMID 37049569, 2023). "Previously, we reported that soy protein concentrate (SPC) with low or high levels of isoflavone (LIF or HIF) protected young obese Zucker rats from developing liver steatosis." (PMID 39529929, 2024). "LIF expression in the circulation is correlated with the severity of liver steatosis." (PMID 37049569, 2023). "Moreover, they found that LIF attenuated liver steatosis via binding to LIFR and activating the STAT3 pathway, which provided a rationale for LIF–LIFR to be a potential therapeutic target for NAFLD treatment." (PMID 36077090, 2022).
lung diseases (3 papers, 2012 to 2024). "More evidence is required for the role of LIF in fetal development and neonatal and infantile lung diseases." (PMID 39845245, 2024). "DTL cytokines which correlated significantly with the degree of lung disease (OI) included IL-1RA (r = 0.54), IL-6 (r = 0.53), IP-10 (r = 0.67), LIF (r = 0.52), MCP-1 (r = 0.66) and SDF-1α (r = 0.52)." (PMID 34239039, 2021).
lymph node metastasis (3 papers, 2020 to 2025). "OSCC patients with higher LIF expression, advanced stage, large tumor size, or lymph node metastasis had significantly shorter overall survival." (PMID 31973037, 2020). "We found that patients with positive lymph node metastasis had higher LIF expression." (PMID 31973037, 2020).
non-small cell lung carcinoma (3 papers, 2005 to 2025). A group of at least three distinct histological types of lung cancer, including non-small cell squamous cell carcinoma, adenocarcinoma, and large cell carcinoma. "LIF has been identified as a novel predictive biomarker for resistance to PD1/PD-L1 blockade in non-small cell lung cancer (NSCLC) and bladder cancer patients, highlighting the potential of targeting LIF to enhance immune checkpoint blockade (ICB) therapy." (PMID 39857986, 2025). "Therefore, as first step, we determined if responsiveness to members of the IL-6 family (IL-6, OSM and LIF) were detectable in established lines of malignant human non-small cell lung carcinoma cells." (PMID 16271139, 2005).
oral squamous cell carcinoma (3 papers, 2022). "It has been previously reported that OSM and its related cytokine LIF stimulate actomyosin contractility and matrix remodeling by oral squamous cell carcinoma–derived CAFs." (PMID 35192545, 2022). "LIF expression within oral squamous cell carcinoma tissue promoted cancer cell invasion, and the inhibin beta A subunit gene is a major downstream mediator of these effects." (PMID 35204717, 2022).
respiratory failure (3 papers, 2012 to 2023). The significant impairment of gas exchange within the lungs resulting in hypoxia, hypercarbia, or both, to the extent that organ tissue perfusion is severely compromised. "Similar to IL-6 levels being a predictive factor in respiratory failure, LIF levels may indicate the severity of the infection in patients." (PMID 32595353, 2020). "In opposition to LIF-deficient lungs, the additional absence of LIF in the IGF-I-null background of mutant mice aggravates the prenatal pulmonary immature phenotype and these mice die due to respiratory failure." (PMID 22291973, 2012).
sarcoma (3 papers, 2007 to 2025). A usually aggressive malignant neoplasm of the soft tissue or bone. "Early effects of Trabectedin (<12M) include the exhaustion of B cells, activation of T and NK cells, and increase of LIF gene expression associated with control of stemness properties of sarcoma cells." (PMID 40007535, 2025). "In the original protocol, we used iPSC lines maintained on an STO cell line transformed with neomycin resistance and LIF genes (SNL) stromal feeder cells in a culture dish coated with growth factor-reduced Matrigel, which was extracted from the Engelbreth–Holm–Swarm mouse sarcoma cell line." (PMID 36109564, 2022).
schizophrenia (3 papers, 2015 to 2024). A major psychotic disorder characterized by abnormalities in the perception or expression of reality. "And particular variants of the LIF gene are significantly associated with the diagnosis of schizophrenia, especially in patients with hebephrenic SCZ." (PMID 38979494, 2024). "Several of these genes have already been implicated in psychiatric disorders, such as LIF, which is located on 22q12.1–q12.2, a particular region known to be a hot spot for schizophrenia, and carries a SNP significantly associated with the disorder." (PMID 33276438, 2020).
ulcerative colitis (3 papers, 2008 to 2022). An inflammatory bowel disease involving the mucosal surface of the large intestine and rectum. "LIF levels are increased in inflammation, as demonstrated by high levels of LIF in patients with ulcerative colitis." (PMID 18801170, 2008).
viral pneumonia (3 papers, 2021 to 2022). Inflammation of the lung parenchyma that is caused by a viral infection. "Leukemia inhibitory factor (LIF) is essential to resist the cytokine storm in the lungs in the period of viral pneumonia." (PMID 35281790, 2022). "In viral pneumonia, presence of leukemia inhibitory factor (LIF) to opposing the cytokine storm in the lung is necessary." (PMID 33629351, 2021).
airway hyperresponsiveness (2 papers, 2014 to 2025). "Inhibition of LIF signaling also subdued RSV induced airway hyperresponsiveness, demonstrated by respiratory system resistance (Rn) measurements during a methacholine dose challenge." (PMID 25277705, 2014). "Altogether, these results suggest that LIF expression suppresses lung cell apoptosis, airway hyperresponsiveness, epithelial cell barrier damage, cytokine production and subsequently airway injury." (PMID 25277705, 2014).
allergic disease (2 papers, 2021 to 2024). An immune response that occurs following re-exposure to an innocuous antigen, and that requires the presence of existing antibodies against that antigen. "Cytokines and chemokines involved in tissue injury, infection, and allergic disease, such as IL-5, LIF, LIX, MCP-1, MIP-1a, and MIP-1b, were increased in the USA300-C2406-infected mice." (PMID 33573328, 2021). "Other cytokines and chemokines such as IL-5, LIF, LIX, MCP-1, MIP-1a, and MIP-1b, which are believed to be involved in tissue damage, infection, and allergic diseases, also showed increased production in USA300 infections." (PMID 33573328, 2021). "Thus, responses to allergen in the absence of ILC2-derived LIF become amplified in the lung, leading to inappropriate tissue-localized iBALT reactions similar to those in asthma and allergy, but also to impaired systemic responses." (PMID 39112698, 2024).
Atrophy (2 papers, 2020 to 2022). Any weakening or degeneration, especially through lack of use. "Our data suggest that LIF administration may be an innovative approach to prevent atrophy associated with AMD, through protection of the choriocapillaris." (PMID 34779136, 2022). "The finding that LIF and CT‐1 have protective effects in the NaIO3 model raises the possibility that they may be of value for protecting the CC and thus for preventing atrophy in AMD, potentially in combination with other approaches that are currently pursued." (PMID 34779136, 2022). "In this context, it might also be perceived that several immune relevant factors, among them leukemia inhibitory factor (LIF) and oncostatin M (OSM), both belonging to the IL-6 cytokine family, increase with age and seem to change the intrathymic microarchitecture leading to thymic atrophy." (PMID 33233845, 2020).
benign prostatic hyperplasia (2 papers, 2022). A non-cancerous nodular enlargement of the prostate gland. "As expected, the expression level of LIF in PCa tissues was significantly increased compared with that in benign prostatic hyperplasia tissues." (PMID 35654787, 2022). "Second, the expression levels of LIF in PCa (n = 30) and benign prostatic hyperplasia tissue samples (n = 30) were determined by qRT-PCR." (PMID 35654787, 2022).
cerebral infarction (2 papers, 2022 to 2023). An ischemic condition of the brain, producing a persistent focal neurological deficit in the area of distribution of the cerebral arteries. "LIF protects neurons by reducing oxidative stress during cerebral infarction by upregulating SOD3 expression." (PMID 36792628, 2023).
Cerebral ischemia (2 papers, 2012 to 2020). Restriction of arterial blood supply to the brain associated with insufficient oxygenation to support the metabolic requirements of the tissue. "Indeed, it has been shown that LIF is up regulated in astrocytes and neurons after cerebral ischemia as well as in astrocytes after cortical brain injury, suggesting a role of LIF in neuronal repair or protection." (PMID 22894638, 2012).
chronic endometritis (2 papers, 2018 to 2023). A non-granulomatous or granulomatous chronic inflammation of the endometrium. "The statistical analysis showed significant correlations between chronic endometritis and the levels of TNF-α, IL-1β, and LIF cytokines (p < 0.0001), and also between chronic endometritis and hysteroscopic findings (p < 0.0001)." (PMID 37835791, 2023). "As regards the uterine cytokines, we found higher levels of IL-1β and TNF-α, and lower levels of LIF in patients with chronic endometritis, regardless of the KIR genotype." (PMID 37835791, 2023).
colon adenocarcinoma (2 papers, 2019 to 2024). "A study involving colon adenocarcinoma (C26c20) and recombinant LIF-induced CAC mouse models revealed elevated serum LIF and IL-6 levels." (PMID 38730660, 2024).
endometrial adenocarcinoma (2 papers, 2017 to 2020). "To exam the role of AEA on the expression of LIF, we cultured human endometrial adenocarcinoma cells (RL95-2 cell line) with different concentrations of AEA, and then tested the LIF levels after 24–72 h." (PMID 29085337, 2017).
endothelial dysfunction (2 papers, 2024 to 2025). In vascular diseases, endothelial dysfunction is a systemic pathological state of the endothelium (the inner lining of blood vessels) and can be broadly defined as an imbalance between vasodilating and vasoconstricting substances produced by (or acting on) the endothelium. "Regardless of the inconsistent expression of LIF, it has been shown that LIF increases adhesion molecules via the JAK/STAT3 pathway, inducing inflammation and leading to endothelial dysfunction." (PMID 41006365, 2025).
gastric adenocarcinoma (2 papers, 2023 to 2024). "In contrast, conditioned media from gastric adenocarcinoma cells display LIF-independent stemness and differentiation activities on mESC." (PMID 38137514, 2023). "Because the LIF/LIFR complex promotes an oncogenic development in several cancers, and the expression of LIF mRNA correlates with expression of FGFR4 in GC, then we saought to investigate whether the LIF regulates the expression of the FGFR4 in gastric adenocarcinoma cell lines." (PMID 37945798, 2024).
gout (2 papers, 2022 to 2023). A condition characterized by painful swelling of the joints, which is caused by deposition of urate crystals. "Serum LIF was significantly higher in gout patients during gout flare compared to intercritical gout." (PMID 36850003, 2023). "However, serum LIF protein was significantly elevated in gout patients during flare." (PMID 36850003, 2023). "LIF is a pleiotropic cytokine that modulates autoimmune responses by increasing T-cell numbers and neutrophil accumulation, and disrupts the balance of inflammasome platform activation by stimulating the release of cytokines from multiple cells, whose inflammatory effects lead to gout." (PMID 36313318, 2022). "For further assessment on a protein level, serum TGF-β-LAP and two downstream targets LIF and VEGFA levels were determined in the same individuals with normouricemia, hyperuricemia and gout." (PMID 36850003, 2023).
influenza (2 papers, 2016 to 2024). An acute viral infection of the respiratory tract, occurring in isolated cases, in epidemics, or in pandemics; it is caused by serologically different strains of viruses (influenzaviruses) designated A, B, and C, has a 3-day incubation period, and usually lasts for 3 to 10 days. "Two proteins associated with influenza (LIF, KRT19 (which was also related to HHVs)) and one protein associated with skin and subcutaneous infections (CTNNA3) remained statistically significant at P < 0.05 after FDR correction." (PMID 39143319, 2024). "Knocking down NEK7 had no impact on virus replication, which suggests a non-relevant role of this particular kinase during influenza infection However, knocking down LIF increased virus replication in various influenza A strains." (PMID 27166678, 2016).
medullary thyroid cancer (2 papers, 2012 to 2022). "LIF is able to suppress medullary thyroid carcinoma cell line xenografts, likely through induction of growth arrest and cell differentiation by LIF." (PMID 35204717, 2022). "In fact, in human medullary thyroid cancer cells, it was demonstrated that p44/42 pathway induces autocrine-paracrine growth inhibition via LIF." (PMID 22291973, 2012).
metastatic melanoma (2 papers, 2015 to 2023). A melanoma that has spread from its primary site to another anatomic site. "For this, we analyzed phospho-Smad3 and LIF expression levels by immunohistochemistry in a tissue microarray consisting of 24 benign tumors, 56 malignant tumors, and 20 metastatic melanomas." (PMID 25885043, 2015).
muscular atrophy (2 papers, 2014 to 2022). The loss of muscle tissue due to inactivity or disease. "In this study, we demonstrate that HGF-mediated activation of the satellite cells in hypoxia-induced muscular atrophy combined with LIF can reverse the loss of muscle mass." (PMID 24963862, 2014).
osteoporosis (2 papers, 2022 to 2025). A condition of reduced bone mass, with decreased cortical thickness and a decrease in the number and size of the trabeculae of cancellous bone (but normal chemical composition), resulting in increased fracture incidence. "Most of the skeletal abnormalities in patients with STAT3 deficiency, such as scoliosis and osteoporosis, are due to poor responses to leukemia inhibitory factor (LIF)." (PMID 40040707, 2025).
pancreatic adenocarcinoma (2 papers, 2016 to 2019). "In conclusion, our results indicate that disrupting LIF signaling, which directly fuels oncogenic KRAS-driven pancreatic adenocarcinoma, has an impact on tumorigenicity of KRAS and overcomes the characteristic resistance to chemotherapy." (PMID 31296870, 2019).
Parkinson disease (2 papers, 2015 to 2024). A progressive degenerative disorder of the central nervous system characterized by loss of dopamine producing neurons in the substantia nigra and the presence of Lewy bodies in the substantia nigra and locus coeruleus. "Neuroprotective effects have been attributed to these proteins: LIF protects neuronal precursor cells in the substantia nigra in a murine Parkinson’s disease model in vivo." (PMID 26419927, 2015).
periodontitis (2 papers, 2021 to 2024). An acute or chronic inflammatory process that affects the tissues that surround and support the teeth. "Aydin and Dilsiz reported elevated levels of oncostatin M (OSM), leukemia inhibitory factor (LIF), and IL-11 in the saliva of patients with periodontitis and gingivitis, with levels decreasing following periodontal treatment." (PMID 39410587, 2024). "Additionally, FGF-5 (40.0% vs 25.4%, p=0.03) and LIF (14.7% vs 5.9%, p=0.04) were detected more frequently in participants with periodontitis." (PMID 34385358, 2021).
prostate tumor (2 papers, 2024 to 2025). "Our study shows that the activation of the leukemia inhibitory factor (LIF)/LIF receptor (LIFR) pathway in both prostate tumor and stromal cells, following androgen deprivation therapy (ADT), leads to the development of an immunosuppressive TME." (PMID 38381121, 2024).
psoriasis (2 papers, 2018 to 2020). An autoimmune condition characterized by red, well-delineated plaques with silvery scales that are usually on the extensor surfaces and scalp. "IL-8 expression has previously been correlated with LIF expression in other inflammatory diseases such as psoriasis." (PMID 30263091, 2018). "Also, LIF is thought to be involved in the pathogenesis of psoriasis and the protein is released from lesional skin biopsies from psoriasis patients." (PMID 33224151, 2020).
renal carcinoma (2 papers, 2022 to 2024). A carcinoma arising from the epithelium of the renal parenchyma or the renal pelvis. "In order to evaluate the mRNA expression of LIF mRNA in ccRCC, paired renal carcinoma and paracancer tissues obtained from TCGA and GEO databases, including GSE15641, GSE46699, GSE53757, and GSE66272, were selected for analysis." (PMID 35992780, 2022).
acute endometritis (1 paper, 2026). An acute, usually bacterial infection affecting the endometrium. "Here, we demonstrate that IL-6 family cytokines, Leukemia Inhibitory Factor (LIF) and Oncostatin M (OSM), exert complementary yet distinct immunoregulatory effects that mitigate LPS-induced acute endometritis in vivo." (PMID 42256298, 2026).